POLA1 (DNA polymerase alpha 1, catalytic subunit)
Description:
Catalytic subunit of the DNA polymerase alpha complex (also known as the alpha DNA polymerase-primase complex) which plays an essential role in the initiation of DNA synthesis. During the S phase of the cell cycle, the DNA polymerase alpha complex (composed of a catalytic subunit POLA1, a regulatory subunit POLA2 and two primase subunits PRIM1 and PRIM2) is recruited to DNA at the replicative forks via direct interactions with MCM10 and WDHD1. The primase subunit of the polymerase alpha complex initiates DNA synthesis by oligomerising short RNA primers on both leading and lagging strands. These primers are initially extended by the polymerase alpha catalytic subunit and subsequently transferred to polymerase delta and polymerase epsilon for processive synthesis on the lagging and leading strand, respectively. The reason this transfer occurs is because the polymerase alpha has limited processivity and lacks intrinsic 3' exonuclease activity for proofreading error, and therefore is not well suited for replicating long complexes. In the cytosol, responsible for a substantial proportion of the physiological concentration of cytosolic RNA:DNA hybrids, which are necessary to prevent spontaneous activation of type I interferon responses.
Synonyms: POLA; p180; NSX; PDR; VEODS
Tractability: Small molecule: an approved drug acts on it; a structure with a bound ligand is known; a high-quality ligand is known; it belongs to a druggable protein family. PROTAC: ubiquitination databases record sites on it; a small molecule that binds it is known.
Target class: Enzyme; Transferase
Gene: Protein-coding gene on chromosome X (24,693,864 to 24,996,986, forward strand). Ensembl gene ENSG00000101868.
Subcellular location: Nucleus; Cytoplasm, cytosol
Subcellular location (Human Protein Atlas): Nucleoplasm; Cytosol
Pathways (Reactome):
DNA Replication: Activation of the pre-replicative complex; DNA replication initiation; Polymerase switching; Processive synthesis on the lagging strand; Removal of the Flap Intermediate
Cell Cycle: G1/S-Specific Transcription; Inhibition of replication initiation of damaged DNA by RB1/E2F1; Polymerase switching on the C-strand of the telomere; Telomere C-strand synthesis initiation
Disease: Defective pyroptosis
Gene Ontology:
Molecular function: chromatin binding; DNA binding; DNA polymerase activity; DNA-directed DNA polymerase activity; nucleotide binding; protein binding; protein kinase binding; zinc ion binding; DNA replication origin binding; single-stranded DNA binding; nucleic acid binding
Biological process: DNA repair; DNA replication; DNA replication initiation; DNA replication, synthesis of primer; DNA strand elongation involved in DNA replication; DNA synthesis involved in DNA repair; DNA synthesis involved in UV-damage excision repair; double-strand break repair via nonhomologous end joining; lagging strand elongation; leading strand elongation; nucleotide-excision repair; regulation of type I interferon production; DNA-templated DNA replication; mitotic DNA replication initiation
Cellular component: alpha DNA polymerase:primase complex; chromatin; cytosol; nuclear envelope; nuclear matrix; nucleolus; nucleoplasm; nucleus
Gene-disease validity (ClinGen):
ClinGen rates the evidence that POLA1 causes each of these diseases.
X-linked reticulate pigmentary disorder (X-linked): Moderate.
Homologues: Orthologues: chimpanzee POLA1 (99% identical), macaque POLA1 (98% identical), dog POLA1 (91% identical), pig POLA1 (91% identical), rabbit POLA1 (91% identical), guinea pig POLA1 (90% identical), rat Pola1 (89% identical), mouse Pola1 (88% identical), tropical clawed frog pola1 (72% identical), zebrafish pola1 (69% identical), Drosophila melanogaster PolA1 (40% identical), Caenorhabditis elegans pola-1 (38% identical). Paralogues in human: REV3L (21% identical), POLD1 (16% identical), NEXMIF (11% identical).